DLL4 (delta like canonical Notch ligand 4)
Diseases named in the same sentence as DLL4 in open-access papers (continued):
Sharing a sentence is not in itself a finding about the gene and the disease.
atherosclerosis (13 papers, 2013 to 2025). A disease characterized by the build-up of fatty material and calcium deposition in the arterial wall resulting in partial or complete occlusion of the arterial lumen. "Consistently, blockade of Dll4-Notch signaling using a neutralizing anti-Dll4 antibody attenuated the development of atherosclerosis in LDL receptor-deficient mice." (PMID 41018180, 2025). "Consistently, blockade of Dll4-Notch signaling using neutralizing anti-Dll4 antibody attenuated the development of atherosclerosis in LDL-receptor-deficient mice." (PMID 23531541, 2013). "Nevertheless, in macrophages activation of Dll4/Notch3 has been associated with plaque instability and inhibition of Dll4-mediated Notch signaling in metabolic syndrome has proven to be effective in slowing down the progression of atherosclerosis." (PMID 25629006, 2014). "An anti-Dll4 antibody has been employed to successfully interfere with vascular inflammation and atherosclerosis progression in a mice model of atherosclerosis." (PMID 31191522, 2019). "In this model an anti-Dll4 antibody was able to lessen both macrophage accumulation and atherosclerosis." (PMID 31191522, 2019). "DLL4 blockade has been shown to improve atherosclerosis and metabolic disease while Notch1 blockade promotes browning of white adipose tissue and improves energy expenditure and metabolism." (PMID 31134094, 2019). "It has been proposed that Dll4 and Notch-1 are key regulators of macrophage activation in atherosclerosis." (PMID 27973542, 2016). "Relevantly, global inhibition of Notch ligand Delta-Like Ligand-4 (DLL4) attenuates atherosclerosis by altering the macrophage-mediated inflammatory response." (PMID 27898698, 2016). "Differently from Dll4, in the context of atherosclerosis Jagged1-mediated signaling could be protective, since anti-Jagged1 immunotherapy has been shown to inhibit MDSCs and overcome tumor-induced tolerance by activating T-cell." (PMID 31191522, 2019).
vascular neoplasm (13 papers, 2011 to 2023). A benign, intermediate, or malignant neoplasm arising from vascular tissue including arteries, veins, venous sinuses, lymphatic vessels, arterioles and capillaries. "Long-term DLL4 blockade can lead to the development of vascular neoplasms, while persistent activation of DLL4 has been associated with T-cell acute lymphoblastic leukemia." (PMID 37907742, 2023). "Unfortunately, pre-clinical studies in mice, rats and NHP have also reported anti-DLL4-associated hepatotoxicity characterized by SD and induction of vascular neoplasms in the liver." (PMID 29879147, 2018). "However, anti-Dll4 treatment was later shown to induce a loss of endothelial quiescence and vascular neoplasms, which were proposed to be the main cause of pathology in several organs." (PMID 37745941, 2023). "Moreover, it has been shown that chronic DLL4 blockade causes pathological activation of endothelial cells, disrupts normal organ homeostasis and induces vascular tumours raising important safety concerns." (PMID 29879147, 2018). "However, safety concerns have been arisen since it has been reported that in preclinical models, chronic Dll4 blockade abnormally activates endothelial cells and causes vascular neoplasms." (PMID 23143192, 2012). "Rats and chimpanzees treated with anti-Dll4 antibodies also developed significant liver vascular neoplasms and disease; therefore, we focused our analysis on this organ." (PMID 37745941, 2023). "Sustained treatment with anti-Dll4 antibodies result in abnormal liver pathology and can give rise to vascular neoplasms in various species including monkeys, rats and mice." (PMID 26620208, 2016). "Our results suggest that the inhibition of DLL4-Notch signaling resulted in an increased vascular tumor density." (PMID 23028940, 2012). "Recently, it has also been shown that Dll4 or combined Notch1 and -2-inhibition can lead to development of vascular tumors and hepatotoxicity." (PMID 21533193, 2011). "Dll4 inhibition induces vascular tumors consistent with angiosarcoma in murine models." (PMID 33931674, 2021). "However, long-term blockade of Dll4 was found to lead to the development of vascular neoplasms and other toxicities." (PMID 26213336, 2015). "In this respect, it has been shown that chronic Dll4 blockade induces vascular neoplasms." (PMID 23531541, 2013). "Chronic inhibition of the Notch pathway by Dll4 blockade using inhibitory antibodies may even lead to the induction of vascular neoplasms." (PMID 23143192, 2012). "Therefore, vascular neoplasms are not the cause of the previously reported anti-Dll4 antibody toxicity." (PMID 37745941, 2023). "Alternative approaches could include specifically inhibiting Notch-Jagged protein interactions without inhibiting Notch Dll1/Dll4, as inhibiting in this way does not cause hypersprouting and hyperproliferation which is the likely mechanism leading to vascular neoplasms." (PMID 26620208, 2016). "A recent work described that prolonged (over 8 weeks long) therapy with high dosages of Dll4 inhibitors (much higher than any of the dosages used in this work) can lead to low frequency non-lethal subcutaneous vascular neoplasms and histopathological changes in the liver." (PMID 22279550, 2012).
bladder cancer (10 papers, 2009 to 2025). "We demonstrated for the first time direct interactions between DLL4 and Notch2/3 associated to activation of canonical downstream Notch signaling and increased tumor cell behavior in human bladder cancer cells." (PMID 39951484, 2025). "Further analyses of Notch signaling in bladder cancer can promote the development of tailored anti-DLL4/Notch bladder cancer therapies in the future." (PMID 39951484, 2025). "Here, we analyzed DLL4 and Notch receptor expression, interaction and downstream signaling in human bladder cancer cells." (PMID 39951484, 2025). "In a 3D invasion model of bladder cancer, microtumors with a high level of DLL4 at the invasive front exhibited enhanced invasiveness." (PMID 34831307, 2021). "This supportive role of DLL4 in collective invasion is consistent with previous work examining NOTCH1-DLL4 signaling in HT-1376 bladder cancer cells and other cell models." (PMID 34831307, 2021). "In bladder cancer, it has been reported that compared to approximately 60% of DLL4-negative vessels, 98% of DLL4-positive tumor vessels are surrounded by pericytes and vSMCs cells." (PMID 32373218, 2020). "Compared with Dll4 expression levels in lung, breast, pancreatic and bladder cancer, Dll4 expression in CCRCC has been detected at levels nine-fold higher than those in the normal kidney." (PMID 25364440, 2014). "Previous studies have confirmed that Dll4 expression is an independent indicator of poor prognosis in several types of human malignancy, including lung, breast, pancreatic and bladder cancer." (PMID 25364440, 2014). "Compared to 64.5% of DLL4-negative vessels, 98.7% of DLL4-positive tumor vessels are surrounded by α-SMA-positive pericytes in bladder cancer." (PMID 22007214, 2012). "This is consistent with data from human xenografts and in situ hybridisation data for Dll4 in human bladder cancer and human renal cell carcinoma." (PMID 19844231, 2009). "Serial sections of bladder cancer showed endothelial colocalisation of Dll4 mRNA using in situ hybridisation, and protein using immunohistochemistry." (PMID 19844231, 2009). "This supports the oncogenic role of the NOTCH2/NOTCH3/DLL4 axis in bladder cancer." (PMID 41008920, 2025). "This approach has been demonstrated through the use of gold nanorod-locked nucleic acid (GNR-LNA) biosensors to examine Delta-like ligand 4 (DLL4) expression in a bladder cancer invasion model to reveal that DLL4 expression is upregulated at the invading front of tumor spheroids." (PMID 39409910, 2024). "Furthermore, NOTCH1, which sup-presses basal phenotypes and bladder cancer progression, negatively regulates the formation of a DLL4 expressing subpopulation that promotes collective cancer invasion." (PMID 34831307, 2021). "Further in vitro data correlates DLL4 protein not only with NOTCH2 but also with NOTCH3 receptor, as analysed in different bladder cancer cell lines." (PMID 41008920, 2025).
lung carcinoma (10 papers, 2012 to 2024). "Furthermore, the enhanced Notch responsiveness to DLL4 of the SIRT1-deficient lung cancer-derived ECs was abrogated by the addition of the γ-secretase inhibitor DAPT." (PMID 23028940, 2012). "MDSC-derived Dll4 activates Notch in lung carcinoma cells, boosting TGF-β signaling by binding and activating Smad proteins." (PMID 30154786, 2018). "Knockdown of endothelial Dll4 stimulates the xenograft tumor growth of lung cancer cells through promoting the proliferation of neighboring cancer cells, and vice versa." (PMID 25909170, 2015). "Inhibition of endothelial cell growth and sprouting angiogenesis by DLL4/Notch signaling was enhanced in SIRT1-silenced lung cancer-derived EC and rescued by Notch inhibitor DAPT." (PMID 23028940, 2012). "In contrast, activation of SIRT1 signaling through the use of the small molecules SRT1720 or SRT2183 inhibited DLL4-mediated induction of HEY1 and HEY2 expression, indicating that SIRT1 negatively modulated DLL4/Notch1 signaling in lung cancer-derived ECs." (PMID 23028940, 2012). "The inhibition of endothelial cell growth by DLL4/Notch signaling was enhanced in SIRT1-silenced lung cancer-derived ECs and was rescued by Notch inhibitor DAPT." (PMID 23028940, 2012). "Further, HDAC5 displays a significant upregulation in lung cancer and increases the proliferation and invasion of lung cancer cells through the upregulation of DLL4 (Delta-like protein 4), Notch-1 (Neurogenic locus notch homolog protein 1) and Twist-1 (Twist-related protein 1)." (PMID 35626663, 2022). "Interestingly, endothelial cells were also showed to play a tumor-inhibitory effect on lung cancer growth by Dll4/Notch1/PTEN signaling pathway." (PMID 27215466, 2016). "SIRT1 could stimulate tumor growth by increasing vessel density and downregulating DLL4/Notch signaling in lung cancer." (PMID 26318035, 2015). "In lung carcinoma, MDSCs suppress CD4+ and CD8+ T cell activity, secrete TGF-β, which promotes neoplastic cells proliferation and the expression of Dll4." (PMID 30154786, 2018). "To obtain a more comprehensive understanding of the expression of AFAP1L1 in lung cancer endothelial cells, we assessed the expression density of well-known endothelial cell marker genes (PECAM1), tip cell marker genes (DLL4 and CXCR4) and AFAP1L1 in the t-SNE projection." (PMID 37737201, 2023). "Similarly, the silencing of SIRT1 significantly enhanced HEY1 and HEY2 expression in lung cancer-derived ECs in response to DLL4 stimulation, whereas no changes were observed in unstimulated lung cancer-derived ECs." (PMID 23028940, 2012). "Herein, we report that the nicotinamide adenine dinucleotide 1 (NAD1)-dependent deacetylase SIRT1 can function as an intrinsic negative modulator of Delta-like ligand 4 (DLL4)/Notch signaling in Lewis lung carcinoma (LLC) xenograft-derived vascular endothelial cells (lung cancer-derived ECs)." (PMID 23028940, 2012).
renal carcinoma (10 papers, 2014 to 2023). A carcinoma arising from the epithelium of the renal parenchyma or the renal pelvis. "It was reported that hsa-miR-182-5p is reduced in renal cancer tissues and cell lines and regulates the expression of DLL4 gene, which causes change of tumor microenvironment and tumor inhibition." (PMID 34760693, 2021). "Together, our results suggest that UCA1 is a powerful tumor biomarker, and UCA1-miR-182-5p-DLL4 axis is involved in proliferation, migration, apoptosis and progression of renal cancer, which highlight its potential clinical utility as a promising diagnostic and therapeutic target of renal cancer." (PMID 31996265, 2020). "On the other hand, lncRNA urothelial cancer associated 1 (UCA1) positively regulates the expression of Delta-like ligand 4 (DLL4) through sponging miR-182-5p, and subsequently promotes malignant phenotypes of renal cancer." (PMID 34274028, 2021). "DLL4 overexpression significantly reversed cell proliferation inhibition and migration of renal cancer cells induced by silencing UCA1, and significantly reversed cell apoptosis promotion of renal cancer cells induced by silencing UCA1." (PMID 31996265, 2020). "And DLL4 overexpression significantly reversed cell migration of renal cancer cells induced by silencing UCA1." (PMID 31996265, 2020). "The results indicated that UCA1 promoted tumorigenicity of renal cancer cells via upregulating DLL4." (PMID 31996265, 2020). "Our results showed that the DLL4 specific vector (pcDNA3.1-DLL4) significantly reversed the inhibition of DLL4 expression induced by silencing UCA1 in renal cancer cells." (PMID 31996265, 2020). "Our study reveals that UCA1 functions as a miRNA sponge to positively regulate DLL4 expression through sponging miR-182-5p and subsequently promotes the malignant phenotypes of renal cancer cells, thus playing an oncogenic role in renal cancer pathogenesis." (PMID 31996265, 2020). "DLL4 overexpression significantly reversed cell proliferation inhibition and migration of renal cancer cells induced by silencing UCA1, and remarkably reversed cell apoptosis promotion of renal cancer cells induced by silencing UCA1." (PMID 31996265, 2020). "The high expression of DLL4 in endothelial cells of ovarian 70, breast 71, nasopharyngeal 12 and renal cancer 43 has been reported." (PMID 32373218, 2020). "The results showed that UCA1 expression levels were statistically positively correlated with DLL4 expression levels in renal cancer cell lines and knockdown of UCA1 decreased DLL4 expression in renal cancer cells." (PMID 31996265, 2020). "The results indicated that UCA1 promotes malignant phenotypes of renal cancer cells via DLL4-dependent manner." (PMID 31996265, 2020). "Cumulatively, our results suggest that UCA1-miR-182-5p-DLL4 axis is involved in proliferation migration, apoptosis and progression of renal cancer." (PMID 31996265, 2020). "Meanwhile, we found DLL4 overexpression significantly reversed cell proliferation inhibition of renal cancer cells induced by silencing UCA1." (PMID 31996265, 2020). "The results similarly indicate that DLL4 was down-regulated in invasive ductal carcinoma, renal carcinoma, prostate adenocarcinoma and lung small cell carcinoma all in contrast to their corresponding normal tissues or benign hyperplasia (prostate)." (PMID 27542210, 2016). "Taken together, these findings provide a strong rationale for the combined blockade of VEGF and Dll4-Notch signaling in renal cancer patients." (PMID 25393540, 2014). "Similarly, as model risk genes, studies have indicated that UCA1 positively regulates DLL4 expression by sponging miR-182-5p, thereby playing an oncogenic role in renal cancer pathogenesis." (PMID 37020128, 2023). "UCA1-miR-182-5p-DLL4 axis is involved in proliferation and progression of renal cancer." (PMID 31996265, 2020). "Moreover, DLL4 had been proved to be involved in the malignant behaviors of renal cancer in previous studies." (PMID 31996265, 2020).
renal carcinoma (continued). "Elevated DLL4 protein promoted transcription and translation of proteins operating in essential oncogenic signaling pathways, subsequently promoting malignant phenotypes of renal cancer cells." (PMID 31996265, 2020). "We further determined whether UCA1 regulated the expression of DLL4 in renal cancer cells via miR-182-5p-dependent manner." (PMID 31996265, 2020). "We found overexpressing miR-182-5p decreased DLL4 expression in renal cancer cells." (PMID 31996265, 2020). "Meanwhile, we found knockdown of UCA1 decreased DLL4 expression of renal cancer cells in vivo." (PMID 31996265, 2020). "Moreover, DLL4 overexpression significantly reversed cell apoptosis promotion of renal cancer cells induced by silencing UCA1." (PMID 31996265, 2020). "DLL4-NOTCH signaling is critical for the progression of renal cancer cells." (PMID 31996265, 2020). "We further determined whether DLL4 regulated malignant phenotypes of renal cancer cells via DLL4- dependent manner." (PMID 31996265, 2020). "Moreover, knockdown of DLL4 regulated Notch Signaling of renal cancer cells." (PMID 31996265, 2020). "We found that UCA1 was significantly upregulated in renal cancer cells and UCA1 functioned as a miRNA sponge to positively regulate DLL4 expression through sponging miR-182-5p." (PMID 31996265, 2020). "Knockdown of UCA1 increased DLL1, Jag1, Jag2 and Notch1expression and decreased DLL4, NICD and Hes1 expression in renal cancer cells." (PMID 31996265, 2020). "We found knockdown of UCA1 increased DLL1, Jag1, Jag2 and Notch1expression and decreased DLL4, NICD and Hes1 expression of renal cancer cells in vivo." (PMID 31996265, 2020).